CD44 (CD44 molecule (IN blood group))
Diseases named in the same sentence as CD44 in open-access papers (continued):
Sharing a sentence is not in itself a finding about the gene and the disease.
cancer (continued). "This included the downmodulation of canonical markers associated with both healthy and cancer cell stemness, such as Lgr5 and Cd44." (PMID 38658753, 2024). "CD44 also mediates lymphocyte infiltration, macrophage polarization,and inducing mesenchymal stem cells(MSCs)differentiate into cancer-associated fibroblasts (CAFs)." (PMID 38590654, 2024). "CD44 is associated with a high risk of metastasis, recurrence, and drug resistance in various cancers." (PMID 39145451, 2024). "One study revealed that the knockdown of the Twist2 gene suppressed the expression of ITGA6 and CD44, which are involved in the migration and invasion of cancer cells and are associated with the ECM–receptor interaction pathway." (PMID 38254353, 2024). "CD44, a receptor for hyaluronic acid, is a cancer stem cell marker frequently associated with chemoresistance that can activate STAT3." (PMID 39131380, 2024). "Specifically, the loss of CD44 was associated with an increased likelihood of local cancer recurrence." (PMID 38672650, 2024). "Data collected included the cancer type, sample size, interventions, control, treatment outcome, study type, expression of CD44 variants and isoforms, and effect of CD44 on chemotherapy outcome." (PMID 38542115, 2024). "These cells can overexpress the cancer stem cell marker and iron transporter CD44, a membrane glycoprotein associated with tumourigenesis and cancer metastasis." (PMID 38659936, 2024). "Several miRNAs also regulate post-transcriptionally SLC7A11 levels, which is post-translationally stabilized by an interaction with CD44v9 (a variant of the CD44 stemness marker of several cancers) leading to inhibition of proteosomal degradation in cancer." (PMID 37132605, 2024). "Hereon, our research revealed that PACAP38 downregulated the crucial effector (β-catenin), nuclear transcription factors (LEF1, TCF1/TCF7), and downstream target genes (MMP7, cJUN, c-myc and CD44) associated with the Wnt/β-catenin signaling in cancer cells." (PMID 39619607, 2024). "Tobacco use, a principle high-risk exposure in the development of many cancers, has been correlated with levels of soluble CD44 (solCD44) in saliva in a smoking cessation study by our group." (PMID 39030509, 2024). "In general, CD44 is a promising marker associated with brain metastases in cancer patients, which provides us with the new insight into stratification of patients and therapy clinically." (PMID 38783892, 2024). "HA binds the CD44 variant isoforms (CD44v) abundantly expressed on the surface of cancer cells and tumorigenic cancer stem cells." (PMID 39217459, 2024). "It is consistent with our result of increased CD44-positive cancer stem cell populations in CTGF-deficient spheroids due to activation of Wnt/β-catenin signaling." (PMID 39518936, 2024). "Cluster of differentiation 44 (CD44), a cell surface adhesion molecule overexpressed in cancer stem cells, has been implicated in chemoresistance." (PMID 38542115, 2024). "CD44 expression is also upregulated in cancer cell subpopulations and is a molecular hallmark of cancer stem cells." (PMID 38462618, 2024). "CD44 has been implicated in various cancers, including its role as a potential prognostic marker in RCC." (PMID 38985127, 2024). "For example, aptamers can be selected to specifically target cancer-specific splice variants of CD44, a cell surface receptor overexpressed in many types of cancer cells, including breast, ovarian, and prostate cancers." (PMID 39439717, 2024). "It has been reported that CD44 polymorphisms are associated with susceptibility to different cancers 16-19." (PMID 38903932, 2024). "In recent years, a number of novel functions of CD44 and its associations with cancers have been revealed." (PMID 38783892, 2024). "The activity of the MAPK signaling pathway by CD44 has been associated with the growth of cancer cells." (PMID 38783892, 2024).
cancer (continued). "CD44 is a major receptor for hyaluronic acid (HA), and the partnership of these two molecules is strongly associated with cancer and viral infections." (PMID 38539529, 2024). "EGFR expression is also implicated in CD44+ cell aggregation, with its inhibition disrupting cancer stem cell assembly in TNBC." (PMID 38699644, 2024). "Accumulating evidence indicates that CD44 can regulate numerous cancer‐associated signaling pathways to influence cancer cell motility, EMT, and stemness." (PMID 38783892, 2024). "Pancreatic ductal adenomacarcinoma spheroids in the presence of conditioned medium from cancer-associated fibroblasts (CAFs) had elevated levels of ALDH+/CD44+ CSCs." (PMID 38737455, 2024). "Monoclonal antibodies against different CD44 variant isoforms have recently been taken into account in cancer therapies." (PMID 39091989, 2024). "The downregulation of cancer stem cell-like markers such as CD44 and SOX9, which are associated with GC, inhibits drug resistance in GC16–19." (PMID 38714724, 2024). "CD44, a biomarker linked to cancer, is crucial in understanding the progression and metastasis of the disease." (PMID 38544254, 2024). "CD44 polymorphism rs713330 has been shown to correlate with clinicopathological characteristics in other cancers." (PMID 38903932, 2024). "Co-culturing with cancer-associated fibroblasts (CAFs) enhances the organoid-forming ability of CD44+ cells, as well as the expression of CD44 and OCT-4 at the protein level." (PMID 38256139, 2024). "CD44 is overexpressed in various cancer types and is linked to poor prognosis and increased potential of cancer cells to adhere to bone marrow endothelial cells." (PMID 38355711, 2024). "CD44 has been widely implicated as a cancer stem-cell marker in many cancers, and high CD44 expression strongly contributes to raised tumorigenic mechanisms, such as cell division, proliferation, and metastasis." (PMID 38725628, 2024). "CD44 variant isoforms like CD44v8-10 are usually expressed more in cancer stem cells and metastatic cells than CD44 standard isoforms." (PMID 37461792, 2023). "ERM also interacts in part through its receptor function with CD44, a cell surface glycoprotein abundantly expressed in some cancer stem cells and closely associated with cell motility and cancer metastasis." (PMID 37670313, 2023). "As a splicing factor, TDP-43 can affect alternative splicing of various genes, such as apolipoprotein A-II, RXRG, SC35, SMN, ETF1, BRCA1, schizophrenia-associated TNIK gene, PAR3/NUMB, and cancer stem cell marker CD44." (PMID 37996849, 2023). "CD44 protein and its variant isoforms are expressed in cancer stem cells (CSCs), and various CD44 isoforms can have different functional roles in cells." (PMID 37005380, 2023). "For cell motility, cancer cells secrete hyaluronidases to degrade HA into smaller molecules and cause cleavage of CD44, inducing filopodia formation and promoting cell migration." (PMID 37627173, 2023). "In summary, our results indicated that CD44 was associated with disease prognosis and immune infiltration in pan-cancers." (PMID 37117249, 2023). "CD44 regulates proliferation, invasion, migration, and stemness, and its overexpression is associated with cancer recurrence and metastasis." (PMID 38067149, 2023). "CD44 is an adhesion molecule that binds to the extracellular matrix and is implicated in cancer cell migration, invasion and metastasis." (PMID 36831550, 2023). "This knowledge is powerful, as LMW HA binding to CD44 has been shown to promote cancer-associated inflammation." (PMID 36723776, 2023). "Increased α1 was associated with increased CD44 (cancer stem cells), increased CD3 and 8 (T cells), increased CD56 and 16 (natural killer cells), a decreased T stage, and an increased N stage." (PMID 37654227, 2023). "Activation of the CD44 pathway has been linked to a number of biological processes, including development, cancer metastasis, and cell adhesion." (PMID 37383542, 2023).
cancer (continued). "Among CD44 variants, CD44v9 is considered to be associated with cancer stem cells in various cancers, but few reports have described the interactions between CD44v9 and SPP1." (PMID 37190178, 2023). "The same analysis also revealed the relevance of CD44, classified under the proteoglycans in cancer functional terms, in association with vemurafenib resistance." (PMID 37629086, 2023). "MiR-381 levels have been demonstrated to be inversely linked with the expression of defined cancer stem cell marker genes, including CD44, Sox2, Oct4, Nanog, and ALDH1 in RCC tissues." (PMID 37965067, 2023). "In the present study, we demonstrated that CD44 overexpression is associated with poor prognosis, which suggests that cancer cells strongly expressing CD44 have qualities related to CSCs." (PMID 37108495, 2023). "In contrast, CD44 standard isoform is found in most adult tissues, whereas its variant isoforms are expressed in multiple cancers along with specific normal epithelial tissues." (PMID 36831395, 2023). "Recent evidence shows that overexpression of CD44 is associated with poor prognosis in most human cancers and mediates therapy resistance." (PMID 37958796, 2023). "CD44 is, thus, a vital biological entity associated with the pathogenesis of cancer, and miR34a has been found to have a robust association with cancer stem cell regulation in various cancer types." (PMID 37149609, 2023). "The cancer-associated LR interactions in immune-to-fibroblast subset identified high number of CD44 and VIM receptors interacting with COL1A1 and ITGB1_COL1A2 for the HGSOC histotype." (PMID 38328306, 2023). "Numerous cancers are associated with high CD44 concentrations, including breast, prostate, lung, colon, etc.." (PMID 36671915, 2023). "Some studies also illustrated that several variant isoforms of CD44 are directly linked with the signal pathway of cancer cell migration and invasion." (PMID 36776876, 2023). "Variant CD44 isoforms play critical roles in the development of various cancers through their interaction with osteopontin." (PMID 37239056, 2023). "Mechanistically, CD44 and its variant isoforms can activate different downstream signaling pathways to promote cancer cell invasion and proliferation." (PMID 38023123, 2023). "Due to the high expression of CD44, efforts have been made to investigate the diagnostic and prognostic value of CD44 and its isoforms in cancer." (PMID 37491225, 2023). "Soluble CD44 protein, generated by alternative splicing or shedding from cell membranes by MMPs, has been found in body fluids such as cancer patient serum and arthritic synovial fluid and is associated with a poor disease prognosis." (PMID 37895896, 2023). "It has been well documented that CD44 expression in CSCs is associated with metastasis and capacity resisting to apoptosis of cancer cells." (PMID 37117249, 2023). "Our pan-cancer investigation aimed to illustrate the association of CD44 with immunotherapy response in oncogenesis among varying cancer types and its potential for predicting prognosis in pan-cancer patients." (PMID 37117249, 2023). "In breast tumors, the expression of different CD44 variants is associated with the aggressiveness of the cancer cells." (PMID 36759786, 2023). "A recently published computational study focused on analyzing the membrane-proximal stem region of CD44 for the standard isoform and cancer-associated isoform v6 in rats." (PMID 37509083, 2023). "In particular, the splicing variants of CD44 (CD44v) are overexpressed in cancers and play critical roles in cancer stemness, invasiveness, and resistance to chemotherapy and radiotherapy." (PMID 37185762, 2023). "A quantitative meta-analysis, pooling the results of multiple studies to achieve increasing statistical power, provided multiple lines of evidence for the relationship between CD44 polymorphisms and cancer risk." (PMID 37958796, 2023).
cancer (continued). "CD44 and its variants can also be found in various cancers and tissues, including HCC, peri-HCC tissue, hepatoblastoma, liver tissue with viral hepatitis infection and even normal liver tissue." (PMID 36674932, 2023). "Thereafter, the association between CD44 expression and clinicopathologic characteristics was investigated in pan-cancer datasets." (PMID 37117249, 2023). "The PPI network analysis in STRING indicated the interconnection of ezrin with CD44, which is congruent with literature data reporting that ezrin binds to cell-adhesion molecule CD44 implicated in cancer-cell migration and metastasis." (PMID 37629086, 2023). "Especially, splicing variant isoforms of CD44 (CD44v) are overexpressed in cancers and considered a promising target for cancer diagnosis and therapy." (PMID 37504249, 2023). "CD44 promotes the expression of multidrug resistance genes, and its suppression is associated with enhanced chemosensitivity in cancer cells." (PMID 37953954, 2023). "For instance, VIM and CD44 are associated with mesenchymal phenotypes and are expressed by both mesothelial and carcinoma cells." (PMID 37691350, 2023). "CD44 is a transmembrane glycoprotein whose aberrant expression is associated with invasion and metastasis in various cancers." (PMID 34895045, 2022). "Numerous variant forms of CD44 (CD44v) were confirmed to be related with several malignant tumors and metastasis." (PMID 36004971, 2022). "TGF-β promotes MMP-mediated cleavage of CD44, a cell surface receptor for hyaluronic acid implicated in cancer cell invasion and metastasis." (PMID 35884382, 2022). "The non‐kinase transmembrane glycoprotein, CD44 is overexpressed in several cell types including the cancer stem cells, and is often implicated in cancer development and progression." (PMID 35522104, 2022). "Since this discovery, many studies have underlined the importance and expression of CD44 in different cancers." (PMID 35346305, 2022). "HNSCC cancer stem cell (CSC) marker CD44, integrin beta 4 (ITGB4), and small GTPase Rac2 were linked to the terms “Cell leading edge”, “Cell-substrate junction”, and “Focal adhesion”, while further genes showed linkages to one or two GO-terms." (PMID 36076232, 2022). "Previous studies have shown that BRG1 is critical for the expression of CD44 in several cancer cells and demonstrated that CD44 expression is induced by the demethylating agent 5-aza in BRG1 deficient cancer cells." (PMID 35590122, 2022). "CD44, a membrane protein, is a stemness factor in cancer, and its splicing variants are involved in cancer stemness." (PMID 35216168, 2022). "ROS levels in cancer cells were often reduced by the coupling of some CD44 variants to the glutamate-cysteine transporter XCT, making cancer cells resistant to chemotherapy and radiotherapy." (PMID 36268283, 2022). "CD44 is known as one of the cancer stem cell markers and is associated with resistance to various anti-cancer therapies." (PMID 35740662, 2022). "High levels of CD44 are associated with poor prognosis in cancer, and CD44v3 is related to cancer metastasis." (PMID 36605595, 2022). "Engagement of CD44 by HA is associated with diverse cellular functions such as cell adhesion, migration, and invasion, which all contribute to cancer progression and metastasis." (PMID 35198956, 2022). "Most previous studies concerning CD44 variants have focused on the functions of mammalian CD44 standard (CD44s) and specific CD44 variant (CD44v) isoforms in cancer progression." (PMID 36042265, 2022). "The CD44 role in human cancer metastasis (and a possible therapeutic effect) was studied in several cancer cells, but CD44 gene single-nucleotide polymorphism (SNP) and its role in HCC development and clinical features remain poorly investigated." (PMID 35200757, 2022). "Meanwhile, several studies have demonstrated that CD44 linked with Stat3 contributed to cancer initiation and development." (PMID 36678534, 2022).
cancer (continued). "In cancers, two specific alternative splicing variants of CD44, variants 3 (CD44v3) and 6 (CD44v6), containing variable exons 8 and 11, respectively, interact with numerous tyrosine kinase receptors." (PMID 35346305, 2022). "The ability to generate spheres in 3D culture is a hallmark of cancer stemness, which was also shown before for CD44+/CD24− EC cells." (PMID 35406578, 2022). "High expression of CD44 is thought to be associated with poor prognosis in cancer, and in addition to this, CD44 v6 and v3 have been reported to be associated with cancer metastasis." (PMID 36389678, 2022). "In our previous studies, we demonstrated that NGF induces the association between TrkA and CD44 in cancer cells." (PMID 35346305, 2022). "Next, we identified that the cancer cell clusters can be converted to an invasive CD44high state which was induced by TAMs, thus giving rise to CD44-associated signaling mediated cohesive detachment." (PMID 35680853, 2022). "CD44 frequently shows the heterogeneity of alternative spliced variants (CD44v), which are expressed primarily on stem cells and cancer cells, and is thought to contribute to cancer development and progression." (PMID 35707369, 2022). "CD44 is a transmembrane cell-surface glycoprotein that is characterized by its variants displaying differential overexpression in human cancers." (PMID 34976591, 2022). "Among hyaluronidases, TMEM2 was expressed at the highest levels in all cancer cell lines, while CD44s was the most prominent CD44 variant expressed." (PMID 36497283, 2022). "A previous study has shown that as a membrane protein, CD44 and variant CD44v6 were engaged in exosome biogenesis, loading, and delivery in cancer-initiating cells." (PMID 36463112, 2022). "CD44 is a hyaluronan receptor that has been implicated in regulating cell motility and adhesion to promote cancer metastasis." (PMID 33843470, 2021). "The results indicated that there is strong evidence that soluble CD44 and total protein are associated with cancer risk independently of tobacco or alcohol use, age, and gender." (PMID 34830890, 2021). "Further, the expression of CD44, both CD44s and CD44v, is associated with poor prognosis in a majority of cancers, since CD44 signaling leads to EMT, metastasis, and resistance to therapy." (PMID 34150761, 2021). "The binding of antibodies (anti-CD44) to CD44 variants that expressed in a variety of cancers interfere with the binding of HA to CD44 receptor cells and disrupt CD44 matrix interactions." (PMID 34513617, 2021). "Soluble CD44 overexpression blocks cancer cell adhesion to HA and is associated with aggressive growth and unfavorable prognosis for a patient." (PMID 33540535, 2021). "Due to the fact that CD44 is associated with resistance to treatment and poor prognosis of many cancers, it is highly desirable to reveal other aspects of the mechanism of action of ATRA in breast cancer." (PMID 34948142, 2021). "Apart from that, the impact of ITIH5 on anti-cancer treatment remained elusive although CD44 and distinct splice variants have been intensively studied, highlighting an impact on cellular responsiveness to chemotherapeutics." (PMID 33924987, 2021). "In parallel, increased inclusion of CD44 variant exons is known as a marker of carcinoma metastasis and cancer stem cells." (PMID 34086943, 2021). "Various types of cancers, including most head and neck, gastric, lung, colorectal, and breast cancers, and hepatocellular carcinoma express CD44, making it a valuable diagnostic and prognostic marker." (PMID 34064074, 2021). "In cancers, CD44 is associated with clonality, metastatic spreading ability, resistance to chemotherapy and lower overall survival." (PMID 34884696, 2021).